CXCR4 (C-X-C motif chemokine receptor 4)
Diseases named in the same sentence as CXCR4 in open-access papers (continued):
Sharing a sentence is not in itself a finding about the gene and the disease.
ovarian carcinoma (continued). "Pleiotropic effects of CXCR4 in multiple key steps in ovarian cancer suggest that blocking this pathway will improve outcomes for patients with this disease." (PMID 23372646, 2013). "Using fluorescence from eqFP650 to normalize for differences in total numbers ovarian cancer cells, bioluminescence from interaction of CXCR4-CBRN with Ar-CBC was significantly lower in mice that received AMD3100 for five days as compared with vehicle control." (PMID 23372646, 2013). "To facilitate development and optimization of CXCR4-targeted therapies in mouse models of ovarian cancer, we developed a click beetle luciferase complementation reporter for CXCR4 signaling." (PMID 23372646, 2013). "Effects of CXCL12 on ovarian cancer appear to be mediated by CXCR4, one of two known receptors for this chemokine." (PMID 23372646, 2013). "The SDF-1α/CXCR4 axis plays an important role in tumor progression and metastasis and indicates poor prognosis in ovarian cancer patients." (PMID 24094005, 2013). "The inhibition of the chemokine receptor CXCR4 leads to apoptosis in ovarian cancer, hepatoma and chronic lymphocytic leukemia cells, thus demonstrating the importance of this receptor in cell survival and proliferation." (PMID 24259307, 2013). "We used a human tumor xenograft model of metastatic intraperitoneal ovarian cancer to determine to what extent complementation between CXCR4 and β-arrestin 2 detects CXCR4 activation and inhibition in vivo." (PMID 23372646, 2013). "CXCL12 signaling through CXCR4 promotes proliferation, invasion, and metastasis of ovarian cancer cells, all of which contribute to more aggressive disease." (PMID 23372646, 2013). "Others and we have found that CXCR4 is overexpressed in specimens of human ovarian cancer, and its specific ligand CXCL12 is present in the ascitic fluid collected from patients with ovarian carcinoma." (PMID 24384839, 2013). "In this study, TMA was used to assess the expression of CXCL12 and CXCR4 in relation to clinico-pathological characteristics and overall survival of 289 ovarian cancer patients." (PMID 22415233, 2012). "In a study of expression of 14 chemokine receptors, only CXCR4 was expressed within ovarian cancer cell lines." (PMID 22415233, 2012). "Conversely, both knockdown of CXCR4 and use of a neutralizing antibody against CXCR4 in ovarian carcinoma decreased invasion." (PMID 22200669, 2012). "Ovarian cancer cells express CXCR4 and consistently, high concentrations of CXCL12 are detectable in the ascites and tumor masses of ovarian cancer patients, suggesting that this axis accelerates cancer dissemination in the peritoneal cavity." (PMID 24213462, 2012). "We chose to assess the effects of manipulating expression of the chemokine receptor CXCR4 on peritoneal tumour deposits, as we, and others, have found this receptor to be important in ovarian cancer growth and spread 8, 13–15." (PMID 22322968, 2012). "This is in contrast with other studies that showed that CXCR4 expression was an independent prognostic factor for poor survival in epithelial ovarian cancer patients." (PMID 22415233, 2012). "As the CXCR4/CXCL12 pathway is involved in the metastasis of tumour cells, this has important implications for the survival of ovarian cancer patients where the main cause of death is attributed to metastasis." (PMID 22415233, 2012). "The CXCR4 promoter was used to mediate tumor selective replication of the vector, as it exhibits superior activity in both established human ovarian cancer cells and patient-derived primary tumor tissues." (PMID 22022379, 2011). "Further, we demonstrated that there was selectivity in replication with the CXCR4 promoter, as indicated by a higher level of replication in the ovarian cancer cells, when compared to control fibroblasts." (PMID 22022379, 2011). "Another potential therapeutic target is CXCR4, the only chemokine receptor found to be expressed on ovarian cancer." (PMID 22022379, 2011).
ovarian carcinoma (continued). "In vitro studies directly demonstrated that, in the presence of CXCL12, CXCR4 controls both ovarian cancer cell proliferation and migration, through the activation of the ERK1/2 and Akt pathway." (PMID 20049170, 2010). "Prominent CXCR4 staining of the tumor cells was observed in a number of mammary, pancreatic, prostate, cervical and ovarian carcinomas." (PMID 19116653, 2008). "If HER2/neu expression is of biological relevance and not merely reflecting a more advanced stage of the disease, other than CXCR4-mediated HER2/neu activities have to be explored for ovarian cancer." (PMID 17245339, 2007). "Another report suggested that CXCR4 knockdown could mediate the PI3K/AKTmTOR pathway to enhance PTX resistance in ovarian cancer." (PMID 40830812, 2025). "One of the most studied chemokine pathways in ovarian cancer is the CXCL12/CXCR4 axis." (PMID 40362280, 2025). "In ovarian cancer, CXCR4 was detected among 681 hypo methylated-upregulated genes while PTEN, and FOXO-1 were mentioned among the hypermethylated repressed genes and in vascular smooth muscle cell (SMC), vascular injury increased PTEN/AKT signalling through CXCL12- HIF-1alpha." (PMID 38704478, 2024). "In the present study, CXCR4 inhibition was evaluated in human ovarian cancer cells." (PMID 39700131, 2024). "Similar findings were reported by a study on ovarian cancer cell lines, in which mifepristone reduced gap closure, and this was linked to an inhibitory effect of mifepristone on the SDF-1/CXCR-4 axis with downstream suppression of the PI3K-Akt and MAPK signalling pathways." (PMID 39201464, 2024). "In this context, various cancer cells demonstrate a significant expression of functional CXCR4 on the cell surface including A549 lung cancer, SK-OV-3 ovarian cancer, brain tumors like CCF-STTG1 astrocytoma, HT-29 colon adenocarcinoma, and much more tumor entities." (PMID 39420354, 2024). "Second, membrane protein that could potentially become an ovarian cancer biomarker is CXCR4, which can activate several downstream proteins." (PMID 39033780, 2024). "However, it is notable that high CXCR4 expression was found to be significantly favorable in ovarian cancer in that study." (PMID 37749552, 2023). "In addition, the CXCL12/CXCR4 biological axis plays an important role in the progression of several cancers, including ovarian cancer and squamous cell carcinoma." (PMID 35893797, 2022). "Our findings suggest that high CXCR4 at diagnosis might identify, within the category of patients with poor prognosis ovarian cancer (R > 0), patients that could benefit from bevacizumab treatment." (PMID 35406620, 2022). "CXCL12/CXCR4 also enhances cell migration to promote the progression of human ovarian cancer." (PMID 35893797, 2022). "Nevertheless, it remains unknown whether CXCR4-mediated signaling in ovarian cancer is involved in PI3K/Akt/mTOR pathway regulation and impacts EMT and CSC characteristics, invasion and metastasis." (PMID 35681259, 2022). "SDF-1 and CXCR4 were positively correlated in epithelial ovarian cancer staging (P<0.001)." (PMID 35545781, 2022). "We first pathologically analyzed CXCR4 expression in 61 invasive ovarian cancer (OC) tissues." (PMID 35681259, 2022). "Our data suggest that CD44v6-O-MWNTS/DOTAP could significantly improve the delivery and uptake effectiveness of CXCR4 siRNA and clinical drug including Gemcitabine and Oxaliplatin for the treatment of ovarian cancer." (PMID 34307366, 2021). "CXCR4 is expressed in a variety of malignant tumors such as breast, prostate, and ovarian cancers." (PMID 34307366, 2021). "CXCR4 is closely related to the migration, invasion, and metastasis of ovarian cancers." (PMID 34307366, 2021). "The thermo-sensitivity of ovarian cancer cells can be restored through blockage of the CXCR4 axis." (PMID 33472580, 2021).
ovarian carcinoma (continued). "We thus concluded that the obtained CD44v6-O-MWNTS could effectively load drugs and CXCR4 siRNA, internalized by cancer cells and realized notable in vitro and in vivo inhibitory function against ovarian cancer growth." (PMID 34307366, 2021). "The expression of CXCR4 was decreased by CD44v6-O-MWNTS/drug/DOTAP/siRNA in ovarian cancer cells." (PMID 34307366, 2021). "Based on the ceRNA hypothesis, novel mRNA-miRNA-lncRNA regulatory networks (TACC3-hsa-miR-425-5p-FUT8-AS1 and CXCR4-hsa-miR-146a-5p-LINC00665/LINC01535) in ovarian cancer were successfully constructed." (PMID 33123295, 2020). "Blocking the CXCR4 axis restored the thermo-sensitivity of ovarian cancer cells." (PMID 33276524, 2020). "Moreover, CXCR4-expressing ovarian cancer cells have more mesenchymal characteristics and more invasive capacity." (PMID 32423054, 2020). "Thus, CXCR4 blockade in ovarian cancer prevents immunosuppression and improves the outcome of immunotherapy." (PMID 33096815, 2020). "However, there were few researches focused on the function of TACC3-miR-425-5p and CXCR4-miR-146a-5p/ hsa-miR-150-5p in ovarian cancer." (PMID 33123295, 2020). "In addition, VEGF-A and SDF-1a/CXCR4 axis also induce neo-angiogenesis synergistically in human ovarian cancers." (PMID 33330455, 2020). "In ovarian cancer cells, CXCR4 induces MAPK activation and cell proliferation." (PMID 33096815, 2020). "The response to immunotherapy in ACC might also benefit from antagonizing CXCR4, as shown for hepatocellular carcinoma, pancreatic, breast and ovarian cancer." (PMID 33281749, 2020). "Moreover, high levels of CXCL12 were detected in ascitic fluid from patients with ovarian cancer, and some authors proposed the CXCR4/CXCL12 pair as a molecular target in ovarian cancer." (PMID 31703453, 2019). "Among solid tumors, ovarian cancer shows a cooperation between Notch and CXCR4 signaling." (PMID 30154786, 2018). "In addition to driving hematopoietic cells as well as breast and prostate cancer cells to the bone, CXCR4/SDF-1α signaling has also been shown to promote ovarian cancer metastasis and is a predictor of poor prognosis in ovarian cancer." (PMID 30261690, 2018). "By regulating this chemokine system, Notch might influence also the immunosuppressive function exerted by CXCR4 signaling in ovarian cancer." (PMID 30154786, 2018). "Our results suggest that mifepristone inhibit SDF-1/CXCR4 signaling axis, may have preventive and therapeutic effects on ovarian cancer metastasis." (PMID 28938623, 2017). "Furthermore, expression of the chemokine CXCR4 has been found in 59% of ovarian cancers, and CXCL12 in 91% of ovarian cancers; both have been associated with decreased disease free survival." (PMID 27213343, 2016). "CXCR4 blocking antibody may inhibit the signaling pathways, metastasis and tumor cell proliferation in ovarian cancer." (PMID 25999622, 2015). "Thus, in human ovarian cancer cells CXCR4 and CD133 expression identified a discrete population with stem cell properties that regulated tumor development and chemo resistance." (PMID 26020117, 2015). "Moreover, when human ovarian cancer cells were isolated from 37 primary ovarian cancer, an extremely variable level of CXCR4 and CD133 expression was detected." (PMID 26020117, 2015). "However, limited data are available on the expression levels of SDF-1 and CXCR4 variants and CXCR7 in human epithelial ovarian cancer." (PMID 24765189, 2014). "Assessing CXCR4 expression could provide better prognostic information for patients with ovarian cancer and be used as a novel therapeutic target." (PMID 24658065, 2014). "Furthermore, indirect support comes from another prior report demonstrating the induction of mitotic catastrophe in ovarian cancer cells upon inhibition of CXCR4 activation." (PMID 25359780, 2014).
ovarian carcinoma (continued). "Therefore, the present study aimed to characterize the expression pattern and levels of SDF-1 and CXCR4 transcript variants and CXCR7 in epithelial ovarian cancer and healthy human ovaries." (PMID 24765189, 2014). "It indicated that the ethnicity or geographic settings may contribute to the infection of CXCR4 expression on the prognosis of ovarian cancer." (PMID 24658065, 2014). "Limited data are available with regard to CXCR4 mRNA expression in epithelial ovarian cancer." (PMID 24765189, 2014). "The RT-PCR results showed that LPA increases the mRNA expression of CXCR4 in ovarian cancer cells." (PMID 24765180, 2014). "Our results showed that high CXCR4 expression was significantly associated with poor prognosis in terms of OS (ES, 2.81; 95% CI, 1.16–6.80; p = 0.022) and PFS (ES, 8.48; 95% CI, 2.13–33.70; p = 0.002) in ovarian cancer patients." (PMID 24658065, 2014). "Therefore, we use the 3D spheroid culturing method to study the mechanisms of CXCR4 regulation in HeyA8 ovarian cancer cell line." (PMID 25514788, 2014). "Thus, we demonstrated that in epithelial ovarian cancer, CXCR4 and CXCR7 mRNA levels remained unchanged." (PMID 24765189, 2014). "Additional studies show that the CXCR4/CXCL12 axis in ovarian cancer may promote peritoneal metastasis as well as metastasis to the lymph nodes." (PMID 24259307, 2013). "A recent study suggests that incorporating an inhibitor of CXCR4 into drug protocols for ovarian cancer may improve outcomes for patients with this disease." (PMID 24094005, 2013). "Moreover, the imaging technology described in this report provides a facile method to assess pharmacodynamics of CXCR4 inhibitors in mouse models of ovarian cancer." (PMID 23372646, 2013). "Also, the chemokine CXCL12 activates the chemokine receptor CXCR4 on endothelial cells, which promotes endothelial cell migration and proliferation in ovarian cancer cells." (PMID 24259307, 2013). "We transduced HeyA8 ovarian cancer cells with lentiviral vectors for CXCR4-CBRN and Ar-CBC." (PMID 23372646, 2013). "Expression of CXCR4 correlated with reduced survival of patients with ovarian carcinoma." (PMID 24384839, 2013). "CXCR4 has been shown to be a predictor of poor survival in nasopharyngeal carcinoma, renal cell carcinoma, gastrointestinal tumours and ovarian cancer." (PMID 22415233, 2012). "CXCR4 is one of the most frequently expressed chemokine receptors in ovarian cancer." (PMID 23109879, 2012). "Inhibition of CXCR4 activity reduces intraperitoneal dissemination of ovarian cancer xenografts." (PMID 20049170, 2010). "A significant correlationbetween TNF-α and CXCR4 expression was found in ovarian cancer biopsies." (PMID 18779872, 2008). "We wanted to evaluate the influence of HER2/neu on ovarian cancer prognosis and to investigate whether compromised survival would correlate with CXCR4 expression and/or SDF-1 abundance." (PMID 17245339, 2007). "An ovarian cancer xenograft mouse model that was generated by the human ovarian adenocarcinoma SK-OV-3 cell line and subsequently appeared as liver metastases, was used to evaluate the putative upregulation of CXCR4 expressed in this additional murine model of another type of cancer." (PMID 35145271, 2022). "Thus, we concluded that the obtained CD44v6-O-MWNTS could effectively load gemcitabine or oxaliplatin, and CXCR4 siRNA, internalized by cancer cells and realized notable in vitro and in vivo inhibitory function against ovarian cancer growth." (PMID 34307366, 2021). "Therefore, modulation of the CXCL12/CXCR4 axis in ovarian cancer could affect multiple aspects of tumor pathogenesis, including immune dysregulation." (PMID 31384667, 2019). "Plerixafor as a CXCR4 inhibitor has been in clinical use in anticancer therapy for over ten years now, with approval for Non-Hodgin ́s lymphoma, but also with promising experimental results for several other solid tumors such as thyroid cancer, pleural mesothelioma, or ovarian cancer." (PMID 31810195, 2019).
ovarian carcinoma (continued). "The NFκB signaling may regulate the expression of CXCR4 in ovarian carcinoma by multiple mechanisms, including those involving three-dimensional collagen type I (as a model of the ECM present at the metastatic sites) and via loss of the breast cancer metastasis suppressor 1 (BRMS1)." (PMID 24384839, 2013). "Therefore, clinical benefits of targeting CXCR4 as part of combination therapy may be greater in patients with ovarian cancer." (PMID 23372646, 2013). "In addition, EGF enhances the expression of CXCR4 as well as migration of ovarian cancer cells." (PMID 23800251, 2013). "In effect, TNFα can amplify the CXCL12 signal, and therefore neutralising TNFα, neutralising CXCL12, antagonising CXCR4 or inhibiting NF-κB may be an effective therapy for ovarian cancer." (PMID 22415233, 2012). "Therefore, we chose to perform an EMSA to explore whether BRMS1 regulates CXCR4 expression through the NF-κB pathway in ovarian cancer cells." (PMID 22200669, 2012). "Thus, studying CXCR4/CXCL12 function in epithelial ovarian cancer, the choice of an incorrect cell controls could bring wrong conclusions." (PMID 20049170, 2010). "Several of the analyzed genes (TGFβ-1, IL19, CXCR4, BMP1, VCAN, and WNT2) showed elevated expression across multiple cancer types in pan-cancer datasets, including lung, colon, and ovarian cancers." (PMID 41348904, 2025). "Overexpression ABCB1, FGF2, CXCR4, and IL6 portends aggressive ovarian cancer behaviors and poor prognoses." (PMID 40507922, 2025). "Several GPCRs are overexpressed in ovarian cancer including the lysophosphatidic acid receptor (LPAR), C-X-C chemokine receptor type 4 (CXCR4), follicle-stimulating hormone receptor (FSHR) and luteinizing hormone/choriogonadotropin receptor (LHCGR)." (PMID 40836974, 2024). "Previous studies have already provided evidence that CXCR4 emerges as a suitable target for imaging and therapy in multiple solid tumors, including ACC, ovarian cancer, neuroendocrine tumors, or SCLC." (PMID 38082196, 2024). "Cervical cancer, malignant pleural mesothelioma, ovarian cancer and renal cell carcinoma secrete CXCL12, which recruits CXCR4 expressing Tregs impaired by the specific CXCR4 antagonist AMD3100." (PMID 38704478, 2024). "Blocking the binding of SDF-1 to its receptor, CXCR4, increases the CD8+ T cell/Treg ratio and reduces the intraperitoneal metastasis of ovarian cancer cells." (PMID 36831623, 2023). "The CXCR4 inhibitor AMD3100 was successfully used in in vitro studies and mouse xenograft models of ovarian cancer to restore taxol chemo-sensitivity and prolong survival." (PMID 38248751, 2023). "Our research demonstrates the impact of CXCR4 silencing in attenuating EMT and characteristics of CSC stemness as well as enhancing the sensitivity of ovarian cancer cells to PTX treatment in vitro and in vivo." (PMID 35681259, 2022). "C-X-C motif chemokine ligand 12 (CXCL12), C-X-C motif chemokine receptor 4 (CXCR4), and CXCR7 can influence the development of endometriosis, Asherman’s syndrome, endometrial cancer, and ovarian cancer." (PMID 36309699, 2022). "The phenotypic/genotypic characteristics of stable ovarian cancer cells, such as EMT and stemness properties, were altered after CXCR4 overexpression or knockdown." (PMID 35681259, 2022). "The only FDA-approved CXCR4 antagonist, AMD3100, sensitizes ovarian cancer to chemotherapy and impairs the epithelial–mesenchymal transition (EMT) when coupled with paclitaxel (PTX)-loaded bovine serum albumin (BSA) nanoparticles." (PMID 35406620, 2022). "CXCR4 can serve as an independent prognostic factor in ovarian cancer, revealing a close relationship between the chemokine axis CXCL12/CXCR4 and ovarian malignancies, which has been reported in many studies." (PMID 35681259, 2022).